CD4 (CD4 molecule)
Diseases named in the same sentence as CD4 in open-access papers (continued):
Sharing a sentence is not in itself a finding about the gene and the disease.
tumor (continued). "We also detected the changes in Treg cells in the subcutaneous tumor-bearing model, and the results showed that LFA-1 knockout decreased the numbers of CD4 + CD25 + Foxp3 + Treg cells in the blood, spleens, and lymph nodes (**P < 0.01, *P < 0.05)." (PMID 37723552, 2023). "Meanwhile, evidence for the presence of IFNγ-producing CD4+ CTL in solid human cancers have been generated by single cell RNA sequencing and flow cytometry analyses of tumors and tumor infiltrates." (PMID 37965314, 2023). "Lastly, a positive correlation was observed between FANCI expression and tumor-infiltration levels of CD8+ T cells, B cells, regulatory T (Tregs), CD4+ T helper 2 (Th2), and macrophage M2 cells." (PMID 37324186, 2023). "This study found that only CD204+ cells, corresponding with macrophages, were higher in tumor areas of BM compared to the primary tumor, whereas CD4+ T cells, CD8+ T cells, and CD+ FOXP3 T cells were higher in the primary tumor." (PMID 37876939, 2023). "The LckCA/KR mice showed defective tumor and viral clearance in these CD8+ T cell-based models but partially rescued the LckCA/CA phenotype in the CD4+ TFH compartment." (PMID 36564464, 2023). "We demonstrated a correlation between CD4+ and CD20+ tumor-infiltrated lymphocytes (TILs) in the primary tumor and clinical outcomes." (PMID 38067231, 2023). "The cytotoxic CD8+ T cell population, together with CD4+ T helper (Th1) cells through the production of IL2 and INFγ, recognize tumor cells presented by antigen-presenting cells (APC)." (PMID 36674836, 2023). "DCs take up tumor antigens and migrate to lymph nodes to activate the IL-2-producing CD4+ (Th1) and tumor-specific CD8+ (Th2) T cells, which migrate to the tumor site and eradicate the viable antigen-positive tumor cells." (PMID 36839774, 2023). "The immunophenotype of tumor cells overlaps with that of other types of ALCL with strong CD30 expression, positivity for cytotoxic markers, frequent CD4 expression, and negativity or focal positivity for T-cell-associated antigens CD3, CD5, and CD7." (PMID 37555981, 2023). "The percentages of tumor-infiltrating CD8+ and CD4+ T cells, respectively, were increased to 10.3% and 8.2% by NvH, and 12.4% and 8.4% by NvIH." (PMID 37450588, 2023). "Current studies generally believe that trends of TILs such as CD4+T cells and CD8+T cells in the tumor microenvironment can predict some tumor conditions." (PMID 37587146, 2023). "It has been suggested that the efficacy of EGFR-TKIs depends mainly on the presence of CD4+ and CD8+ T cells, as treatment significantly enhances the immune responses against the tumor." (PMID 37601668, 2023). "This conversion results in potent inhibition of CD4+ and CD8+ T-cells and significant immunosuppression in tumor settings." (PMID 37165457, 2023). "Neoadjuvant immunotherapy can activate exhausted tumor-infiltrating T cells, improve their TCR activity and metabolic activity, and enable CD4 + regulatory T cells to turn into effector cells." (PMID 37543576, 2023). "Generally, the expression of CD226 in CD4+, CD8+T cells, or Tregs in normal tissues was higher than that in tumor tissues." (PMID 37056782, 2023). "APS4 can effectively regulate the proportion of CD3+, CD4+, and CD8+ T cells in the thymus, peripheral blood, and spleen of S180 tumor-bearing mice in a dose-dependent manner." (PMID 37959774, 2023). "xCELL analysis showed that the immune components among the four subtypes, including tumor suppressors (CD8+ effector, CD8+ central memory, Macrophage M1) and tumor promoters (CD4+ Th2, Macrophage M2), were significantly different (P < 0.001)." (PMID 37540227, 2023). "IL-12 induced tumor-infiltrated CD45+ and proliferative IFN-γ-positive CD8+ T cells and reduced CD4+ FOXP3+ Treg cells." (PMID 36831498, 2023). "The immune checkpoint T-cell immunoglobulin and mucin-domain containing molecule 3 (TIM3) was upregulated in tumour-infiltrating CD8+ and CD4+ T cells." (PMID 37542324, 2023).
tumor (continued). "In the dLNs, tumor-bearing Dnase1l3-KO mice had fewer CD8+ T cells and activated GZMB+CD4+ T cells compared with WT mice." (PMID 37581941, 2023). "Applying Akoya Bioscience OPAL 7-plex mIHC to the first cycle of NACT in the WSG-ADAPT-TN trial (n=66 TNBC patients), the increase in PD-1-+ CD4 and PD-1+ CD8 infiltration in both the tumor and in the stroma were significantly correlated with higher pCR." (PMID 37284197, 2023). "In mice, Sunitinib increased the CD4+ and CD8+ T cells proportion in Tumor-infiltrating lymphocytes." (PMID 37799727, 2023). "IFN-γ is a pleiotropic cytokine known for its anti-tumor function and is mainly regulated by CD8+ and CD4+ T cells during adaptive immune responses." (PMID 37766179, 2023). "A high abundance of tumor mast cells promoted both better OS and progression-free survival, enhancing the accumulation of CD8+ T cells and CD4+ T cells." (PMID 36899891, 2023). "rsPD1 can enhance T cell immunity and rescue virus-specific CD4 and CD8 T cells proliferation during chronic infection and can facilitate anti-tumour immunity." (PMID 37973660, 2023). "Compared with those in the tumor-bearing and cryo-thermal therapy groups, the proportion of splenic CD3+, CD4+ and CD8+ T cells after combination therapy was significantly increased." (PMID 37108179, 2023). "Tumor-infiltrating lymphocytes, one of the major constituents of TME, refers to the lymphocytes that migrate from the blood to the site of the tumor, including CD8+ T cells, CD4+ T cells, B lymphocytes and NK cells." (PMID 38455361, 2023). "TIM-3 and Gal-9 are expressed in OS tumors, and their signaling pathway promotes apoptosis of CD4+ and CD8+ T cells in the tumor microenvironment." (PMID 37329384, 2023). "Strikingly, B cell deficiency increased the frequency and the absolute number of total CD3+ T cells, CD4+ T cells, and CD8+ T cells in tumor-draining lymph nodes." (PMID 37035195, 2023). "Flow cytometry analysis examined the change in CD45+ cells (leukocytes), CD45+CD8+ cells (CTLs), CD45+CD4+ cells (T helper cells), and CD45+CD4+Foxp3+ cells (Tregs) in tumours both 3 and 7 days after the initial treatment day." (PMID 37631324, 2023). "REP TILs were able to respond to activation in the presence of tumor cells; increases in the CD3+ (median 0.72% vs. 1.33%, P = 0.098) and CD4+ (0.46% vs. 1.08%, P = 0.012) T cell IFNγ and TNFα expressions were observed after 6 hours of co-culture." (PMID 37484198, 2023). "Therapeutic cancer vaccines trigger CD4 + and CD8 + T cell responses capable of established tumor eradication." (PMID 37222770, 2023). "The immune inflamed tumors are characterized by the presence of CD4+ and CD8+ T cells and myeloid cells in the tumor parenchyma." (PMID 37284199, 2023). "Radiation has been shown to augment the presentation of TAA by DCs to both CD4+ and CD8+ T cells, thereby reinforcing the ability of the immune system to recognize and target tumor cells." (PMID 37637032, 2023). "We observed significant increases in the percentage of CD4+ and CD8+ T cells in the spleens of PyMT tumor–bearing mice after ablation of CeMCRH neurons." (PMID 37847562, 2023). "The percentage and number of CD4+ and CD8+ T cells within tumor-draining lymph nodes returned back to the baseline levels after clearance of the tumors in AhR-silenced-MOC1-implanted mice." (PMID 37830596, 2023). "scRNA-seq of immune cell isolates from these tumours identified a notable rise in CD8+ cytotoxic T cells and CD4+ helper T cells, as well as a slight increase in natural killer (NK) cells." (PMID 37563469, 2023). "The co‐expression of S100A5 on tumor cells and the exclusive role of S100A5 between CD4+ T and CD8+ T cells reached statistical significance in the whole TMA cohort." (PMID 37414584, 2023). "Though CD4 expressing cells were rarely detected both in untreated and treated KPC tumour's snRNA‐seq, we observed CD4+ cells in untreated tumours using IHC staining." (PMID 38131168, 2023).
tumor (continued). "TIGIT is expressed on NK cells, CD4+, CD8+ T cells and Treg cells and binds to two ligands (CD155 and CD112) that are expressed by tumor cells and other APCs within the TME." (PMID 38275827, 2023). "On the one hand, depletion of METTL3 facilitates anti-tumor immunity by restraining Treg cells, on the other hand, reduced METTL3 in CD4 + T cell impairs humoral immunity by suppressing the differentiation and functional maturation of T follicular helper cell." (PMID 36810281, 2023). "We analyzed CD4+ T cells in a tumor-killing assay and observed that EGFRvIII-DBTE induced anti-tumor cytotoxicity by isolated CD4+ T cells at an E:T ratio of 20:1." (PMID 36915911, 2023). "rHGP lesions revealed a barely detectable signal for both CD4 and CD8 cells throughout the lesions, conversely, we observed an increased number of both immune cell types at the tumour-liver interface of dHGP lesions." (PMID 39516397, 2023). "A total of 22 patients underwent baseline tumor biopsies and, of those, 13 had matched pre- and post-treatment biopsies assessable for change in CD8+ TILs and the change in CD8+/CD4+ ratio." (PMID 37120591, 2023). "We first analyzed the TCGA dataset and found statistically significant differences in the expression of activated CD4+ memory T cells, CD8a+ in tumor cell infiltration and CD8+T lymphocyte cytotoxic factors in tumor tissues with high/low ISG15 expression." (PMID 37217923, 2023). "COX2high CAFs secrete high amounts of prostaglandin E2 (PGE2), which induces the downregulation of molecules important for antigen presentation, including MHC-class II in DCs, and, consequently, impairs CD4+ and CD8+ T cell responses against tumour cells." (PMID 36480035, 2023). "Flow cytometry analysis of LLC-tumor-bearing lungs at day 20 revealed an increased proportion of CD8+ T cells, CD4+ T cells and NK cells following IV BCG treatment, accompanied by enhanced cytotoxic potential evidenced by increased Granzyme B expression." (PMID 37794033, 2023). "Fe3+-TA@HA also promotes the recruitment of CD4+ and CD8+ T cells in mouse tumors and suppresses tumor growth through cytokine secretion." (PMID 38288118, 2023). "CD4+ Th1 cells and CD8+ T-cells are generally regarded as tumor-suppressant, majorly through the activity of interferon gamma (IFN-γ)." (PMID 37681925, 2023). "The changes in the number and distribution of CD4+ and CD8+ T cells suggest that WCP inhibited tumor proliferation probably by activating cellular immunity." (PMID 37110586, 2023). "OC cells overexpressing NLRC5 exhibited slower tumor growth and resulted in higher recruitment of leukocytes in the TME with lower CD4/CD8 T-cell ratios and increased activation of T cells." (PMID 38235131, 2023). "Combination PD-1/CTLA-4 blockade increased the proliferation and infiltration of CD4+ and CD8+ T-cells more than PD-1 blockade alone, and significantly decreased the percentage of tumor infiltrating exhausted LAG3+ TIM3+ CD8+ T cells compared to either alone." (PMID 37449205, 2023). "The TGF-β production can drive the polarization of CD4+ T cells into active Tregs, inhibiting NK cells and CD8+ T cells, which are crucial for tumor growth inhibition." (PMID 37046842, 2023). "Rather than relying on prediction, we sought to utilize a functional approach to NeoAg identification based on monitoring physiological CD4+ and CD8+ T cell responses to tumor-derived antigens." (PMID 37655661, 2023). "Tumours from both groups were removed and paraffin sections were made and stained for IHC to investigate the expression of Ki-67, CD31, CD3, CD4 and CD8 in the transplanted tumours." (PMID 37217923, 2023). "Here we show that tumor cell-derived exosomes (TEX) carrying surface PDL-1, PD-1, Fas, FasL, TRAIL, CTLA-4 and TGF-β1 induce apoptosis of CD8+T and CD4+T cells but spare B and NK cells." (PMID 37542121, 2023).
tumor (continued). "In 4T1-bearing mice treated with 177Lu-DOTA-diZD, the population of CD4+ and CD8+ cells increased, suggesting that 177Lu-DOTA-diZD modulates the tumor microenvironment." (PMID 36632233, 2023). "Reprogramming T cell infiltration and T cell exhaustion improves tumor infiltrating lymphocytes, such as CD8+ or CD4+ T cells." (PMID 36721212, 2023). "Activated T cells, including CD4+ and CD8+ T cells, were found to overexpress PD-1 and CD39 proteins and had an increased percentage of tumor-specific TCR clones." (PMID 36414693, 2023). "The lack of maturation of dendritic cells prevents the activation and proliferation of naïve CD4+ T cells and CD8+-tumor-infiltrating lymphocytes (TILs)." (PMID 37508400, 2023). "The elimination of M2 TAMs in the tumors remodeled the tumor environment, which was evidenced by the enhanced infiltration of CD4 + and CD8 + T lymphocytes, as well as the reduced myeloid-derived suppressor cells (MDSCs) in tumor microenvironments." (PMID 36759822, 2023). "Our in vivo experiment showed that nigericin treatment induced CD4+ and CD8+ T cells to infiltrate into 4T1 tumors, which was regarded as a cold tumor model." (PMID 37370831, 2023). "The functional qualities of CD4+ and CD8+ T cells infiltrating D14 and D21 tumours were examined ex vivo following tumour dissociation." (PMID 37153625, 2023). "Anti-PD-L1 therapy reduced the proportions of intratumoral PD-L1+ lymphoid and myeloid cell populations and induced tumor vascular normalization in a CD8+ T cell dependent manner, while CD4+ T cells impeded these effects." (PMID 36969495, 2023). "According to conventional wisdom, tumor-infiltrating lymphocytes (TILs) are a diverse population of T cells, including CD4+ and CD8+ subpopulations, that are present in the tumor microenvironment (TME)." (PMID 36973645, 2023). "Specific CD4+ and CD8+ T-cell infiltration was very marginally observed in the brains of control mice injected with GL261 parental tumor cells but was observed to a significant extent in GL261 tumors of GL261-challenged mice after GL261-CIITA vaccination." (PMID 36993983, 2023). "The analysis of CD4+ and CD20+ tumor-infiltrated lymphocytes as well as PD-L1 expression on tumor cells make it possible to determine a group of patients with a high risk of recurrence." (PMID 38067231, 2023). "Together, these results suggest that anti-PD-L1 therapy induces CT26 tumor vascular normalization and tumor regression via CD8+ T cells, while CD4+ T cells antagonize these effects." (PMID 36969495, 2023). "Under normal circumstances, CD4+ and CD8+ T cells should be responsible for initiating anti-tumorigenic immunity, but they are exhausted by the surrounding tumor microenvironment via upregulating PD-1 receptors." (PMID 38132318, 2023). "Given the prognostic importance of T cell infiltration in CRC, IHC for CD3, CD4 and CD8 was performed to define the spatiotemporal dynamics of T cell infiltration in MC38 tumours." (PMID 37153625, 2023). "Treated patients had developed significantly more CD4+ and CD8+ T cell infiltrations in the tumor compared to the pre-vaccination state." (PMID 37274252, 2023). "CD4+ and CD8+ tumor-infiltrating lymphocytes (TILs) were digitally assessed on tissue microarray cores and their prognostic role was investigated." (PMID 36833428, 2023). "TECs also induce immune suppressive CD4+ T cells that influence CD8+ T cells through interleukin 10 (IL-10) and transforming growth factor-β (TGF-β) levels, which contribute to tumor immune evasion." (PMID 37666809, 2023). "Increased CD4 (OS, HR =0.395, p=0.007) and CD4+CD8 (OS, HR=0.478, p=0.013) in tumor TLS were protecting factor for survival, but with limited clinical significance." (PMID 36891293, 2023). "Expression of CXCR3, CXCR6, CCR2, and CCR5 differed between trNK cells, ILCs, CD8+ TRM cells, and CD4+ TRM cells, as well as between locations within the tumor and tumor-distal lung tissue." (PMID 37448786, 2023).
tumor (continued). "Given that A2AR expression was significantly enhanced on tumor-infiltrating CD8+ and CD4+ lymphocytes within the tumor microenvironment, we further analyzed the phenotype of A2AR+ T cells relative to their A2AR- counterparts." (PMID 37914685, 2023). "We found increased CD4+ and CD8+ T cell accumulation at the tumor sites of mice treated with Trunc‐LMP2A‐RNP, followed by those treated with FL‐LMP2A‐RNP." (PMID 37890462, 2023). "CD4+ Tem cells and CD8+ Tcm cells, on the other hand, were derived from both normal and tumor tissues." (PMID 37576389, 2023). "In this tumor, MET also had a positive correlation with CD4+ T cells (Rho = 0.438, p = 6.42 × 10−21)." (PMID 37370859, 2023). "These outcomes led to the high expression of cytokines and chemokines (CXCL9 and CXCL10) in T helper 1 (Th1) cells and the recruitment of CD4, CD8 T cells, and M1 macrophages to the tumor area." (PMID 38106403, 2023). "Activation of CD4 lymphocytes then leads to cytokine secretion and assists CD8 lymphocytes in mediating the anti-tumor response." (PMID 37514190, 2023). "Previous studies have demonstrated that increased CD4+CD25+FoxP3+ Treg cells in RCC were related to worse outcomes, and the FoxP3+ tumor cells have been detected in the tumor–normal tissue borders." (PMID 37569676, 2023). "Here, we analyzed the proportions of CD3+CD4+ T cells, CD3+CD8+ T cells, and MAIT cells from different groups in the tumor tissues and in the peripheral blood mononuclear cell (PBMC) using FCM." (PMID 36999930, 2023). "High levels of total CD3+, CD4+ and CD8+ tumor infiltrating lymphocytes (TILs), as well as stromal and intraepithelial CD8+ compartments, significantly predicted good pathological response to NT." (PMID 37537787, 2023). "The CD3+CD4+, CD3+CD8+ and NK cells in tumor from RNF8−/− mice were obviously lower than RNF8+/+ mice, LAC treatment significantly increased infiltration of CD3+CD4+, CD3+CD8+ and NK cells in tumors both in RNF8+/+ and RNF8−/− mice." (PMID 37391451, 2023). "Flowcytometry analysis of the tumor infiltrating immune cells showed that mRIP3 overexpression enhanced tumor immune suppressive CD11b+Gr1+MDSC cells and reduced CD8+ T cells, but the ratio of CD4+ T cells remained unaltered." (PMID 37005412, 2023). "Tumor‐infiltrating lymphocytes, composed of CD8+ T cells, CD4+ T cells, B lymphocytes and NK cells, are lymphocytes infiltrated to the TME from the blood." (PMID 36762766, 2023). "The regressing tumors showed increased CD4 cytotoxic T lymphocyte (CTL) infiltration and enhanced tumor HLA-II expression compared to progressing tumors." (PMID 37185301, 2023). "Top panel, CD8 depletion in MOVCAR 5009 tumor-bearing WT mice abrogated OV-CXCR4-A treatment-mediated control of tumor growth (p = 0.03), which was more pronounced compared with depletion of CD4+ T cells." (PMID 36875325, 2023). "These remarks notwithstanding, in recent years either clinical and preclinical studies put emphasis on the direct involvement of CD4 T cells and especially CAR-T cells in tumor control." (PMID 36593069, 2023). "In pretreated tumor samples, IHC results showed that patients with high levels of GC had lower numbers of tumor infiltrating CD3+ (p=0.001), CD8+ (p=0.059), and CD4+ (p=0.002) cells compared to those with low levels of GC." (PMID 37114049, 2023). "In mice’s tumor tissues, the BZD group had more CD3+, CD4+, and CD8+ T cells than the control group." (PMID 37799727, 2023). "In this patient cohort, we show that the presence of immune biomarkers in the tumour microenvironment, especially CD3 and CD4, had significant impact on PFS." (PMID 37527282, 2023). "We calculated the proportion of each immune infiltrated cell type and observed that a number of T cell subgroups, such as CD4 T, CD8 T, Gamma delta T, Tcm, and Tex, were highly infiltrated in tumor samples than those in normal samples." (PMID 36849756, 2023).